PSG1 (pregnancy specific beta-1-glycoprotein 1)
Synonyms: PS-beta-G-1; PSBG-1; FL-NCA-1/2; PS-beta-C/D; CD66f; B1G1; PSBG1; PSGGA; PBG1; PSG95; PSGIIA; SP1
Tractability: Antibody: UniProt places it where antibodies can reach, with high confidence; its Gene Ontology location is reachable by antibodies, with high confidence; UniProt predicts a signal peptide or a membrane-spanning region.
Gene: Protein-coding gene on chromosome 19 (42,866,464 to 42,879,822, reverse strand). Ensembl gene ENSG00000231924.
Subcellular location: Secreted
Pathways (Reactome):
Hemostasis: Cell surface interactions at the vascular wall
Gene Ontology:
Molecular function: protein binding
Biological process: female pregnancy
Cellular component: extracellular region
Genetic constraint (gnomAD): Loss-of-function variants: 60 observed, 39.24 expected, observed/expected ratio (o/e) 1.53, 90% interval 1.24 to 1.86. The synonymous counts are far from expectation, so gnomAD's model fits this gene poorly and the ratio says little. Missense variants: 801 observed, 511.59 expected, observed/expected ratio (o/e) 1.57, 90% interval 1.48 to 1.66. Synonymous variants: 254 observed, 185.06 expected, observed/expected ratio (o/e) 1.37, 90% interval 1.24 to 1.52.
Homologues: Orthologues: chimpanzee PSG1 (93% identical). Paralogues in human: PSG8 (92% identical), PSG3 (91% identical), PSG7 (89% identical), PSG4 (88% identical), PSG6 (87% identical), PSG9 (84% identical), PSG5 (67% identical), PSG2 (67% identical), PSG11 (65% identical), CEACAM1 (41% identical), CEACAM5 (38% identical), CEACAM8 (37% identical), and 12 more.
Diseases named in the same sentence as PSG1 in open-access papers:
PSG1 is named in the same sentence as 24 diseases in open-access papers, as found by Europe PMC text mining. Sharing a sentence is not in itself a finding about the gene and the disease. The quoted sentences say what the papers report.
preeclampsia (6 papers, 2019 to 2024). Preeclampsia is a hypertensive disorder of pregnancy that is characterized by new-onset hypertension with proteinuria presenting after 20 weeks of gestation, and depending on mild or severe forms may initially present with severe headache, visual disturbances, and hyperreflexia. "Thus, we hypothesize that preeclampsia may be associated with this decline in PSG1 levels." (PMID 38540713, 2024). "We previously found that pregnancy-specific beta-1-glycoprotein 1 (PSG1) levels were decreased in the serum of individuals with early-onset preeclampsia (EOPE)." (PMID 38540713, 2024). "There is evidence that adverse pregnancy outcomes, such as fetal growth restriction, premature delivery, and preeclampsia, are related to reduced blood levels of PSG1 in pregnant women, but there are few reports examining PSG9." (PMID 36980442, 2023). "Although differences in levels of PSG7, PSG9 and PSG1 proteins (all encoded by polymorphic pseudogenes) have been proposed as biomarkers for preeclampsia, no information regarding the individual genetic variability of these genes was provided in these studies." (PMID 39488654, 2024). "Abnormally low levels of PSG1 in women with preeclampsia may reflect dysfunctional or stressed STBs, which may in turn contribute to the pathogenesis of this placental syndrome." (PMID 31683744, 2019). "However, the functional mechanism of PSG1 in the trophoblast of preeclampsia is still unclear." (PMID 38540713, 2024). "Studies have reported that corticotropin releasing hormone (CRH), PSG1 and CYP19A1 are directly related to the development preeclampsia." (PMID 33890634, 2021).
colitis (5 papers, 2021 to 2024). Inflammation of the colon. "Likewise, mice administered PSG1 showed increased numbers of Tregs in the colonic lamina propria, a response which proved protective in a model of colitis." (PMID 36120102, 2022). "PSG1 is a biological activator of TGF-β and reduces inflammation in a dextran sodium sulfate-induced murine colitis model." (PMID 35205121, 2022). "PSG1 and PSG9 have previously been confirmed to activate latent TGF-β1, and PSG1 can also inhibit dextran sodium sulfate-induced colitis in mice in a TGF-β-dependent manner." (PMID 34531852, 2021). "In addition, Ganoderma lucidum polysaccharide (PSG-1) and Codonopsis pilosula polysaccharide (CPP1-2-1) can alleviate inflammatory damage in mice with colitis." (PMID 39202931, 2024).
cervical cancer (3 papers, 2020 to 2025). A primary or metastatic malignant neoplasm involving the cervix. "In cervical cancer, PSG1 gene amplification and overexpression have been observed." (PMID 40806565, 2025).
abortion (2 papers, 2019 to 2024). the ending of pregnancy by removing a fetus or embryo before it can survive outside the uterus. "Meanwhile, using PRM, we identified three proteins that were closely related to abortion, B4DTF1 (highly similar to PSG1), P11464 (PSG1), and B4DF70 (highly similar to Prdx-2)." (PMID 31636515, 2019).
Miscarriage (2 papers, 2023 to 2024). A pregnancy that ends at a stage in which the fetus is incapable of surviving on its own, defined as the spontaneous loss of a fetus before the 22th week of pregnancy. "Furthermore, PRM technology was employed to validate three proteins—CD45, PSG1, and Prdx-2—which were found to be closely associated with miscarriage." (PMID 37587463, 2023).
COVID-19 (1 paper, 2024). A disease caused by infection with severe acute respiratory syndrome coronavirus 2. "Our study showed a decrease in PSG (PSG1-6, 7, 8, 9, 11) levels with COVID-19 in the maternal placenta." (PMID 38338886, 2024).
gastric cancer (1 paper, 2023). A primary or metastatic malignant neoplasm involving the stomach. "In particular, PSG1 is increased in gastric cancer and is used as a biomarker for the diagnosis of this neoplasia." (PMID 37296761, 2023). "Public databases have shown that PSG1 is highly expressed in gastric cancer, yet the role of PSG1 in oncology is not well understood." (PMID 37296761, 2023).
growth retardation (1 paper, 2022). "According to logistic regression analysis results, serum PSG-1 did not affect the risk of intrauterine growth retardation in pregnant women (p>0.05)." (PMID 34755504, 2022).
pancreatic ductal adenocarcinoma (1 paper, 2025). An infiltrating adenocarcinoma that arises from the epithelial cells of the pancreas. "In pancreatic ductal adenocarcinoma (PDAC), PSG1 expression has been detected in tumor tissues." (PMID 40806565, 2025).
placental insufficiency (1 paper, 2022). Failure of the placenta to deliver an adequate supply of nutrients and oxygen to the fetus. "Serum PSG-1 levels may be lower in complicated pregnancies due to problems related to placental insufficiency and FGR." (PMID 34755504, 2022).
Stroke (1 paper, 2022). Sudden impairment of blood flow to a part of the brain due to occlusion or rupture of an artery to the brain. "Another limitation of this study is that the impact of PSG1-Fc in post-stroke mice was only examined at one timepoint." (PMID 36120102, 2022).
tumor (8 papers, 2006 to 2025). "Its increased levels were associated with an immunosuppressive tumor microenvironment, as PSG1 upregulates cytokines such as IL-10 and TGF-β, which can facilitate immune escape." (PMID 40806565, 2025). "For instance, 19q13 is associated in tumor tissues of placental origin with complete extinction of eight clustered genes, namely pregnancy-specific beta-1-glycoproteins PSG-1, -2, -3, -4, -5, -6, -9 and -11." (PMID 16640784, 2006). "However, administration of PSG-1 significantly suppressed xenograft tumor growth through induction of apoptosis in CT26 tumor-bearing mice in vivo." (PMID 31308852, 2019). "Furthermore, PSG-1 is touted to be anti-cancerous in that it could increase phagocytic ability and production of NO and ROS in S-180 tumor cells by activating TLR-4, MAPK, Akt and NF-κB." (PMID 29344411, 2017). "In another studies, PSG-1 can increase cAMP and PKA activities and promote lymphocyte proliferation and macrophage phagocytic activity to activating host immune function in tumor-bearing mice." (PMID 33935714, 2021). "In CT26-bearing mice, PSG-1 induced apoptosis by enhancing the antitumor immune response and activate macrophages through TLR4-dependent signaling pathways to inhibit tumor growth." (PMID 33935714, 2021). "Additionally, the Ganoderma atrum polysaccharide (PSG-1) activated macrophages and increased the production of TNF-α, IL-1β, and NO via p38 MAPK in the murine CT26 tumor model." (PMID 41019059, 2025).
cancer (3 papers, 2020 to 2025). A tumor composed of atypical neoplastic, often pleomorphic cells that invade other tissues. "For instance, PSG1 (Pregnancy specific beta-1-glycoprotein 1), an immunoglobulin highly expressed in several kinds of cancers, involves in the regulation of placental growth factor (PGF), TGF-β-mediated vascular endothelial growth factor (VEGF) and the activation and proliferation of T-cell." (PMID 41323395, 2025). "The RNAs with significantly higher expression levels in cancer tissues than in normal tissues include PELATON, INSL4, PSG1, PSG4." (PMID 35454778, 2022).
immune dysfunction (1 paper, 2017). "PSG-1 has been shown to relieve immune dysfunction through the upregulation of serum IL-2, which increases lymphocyte proliferation and subsequently, longevity." (PMID 29344411, 2017). "It has been comfirmed that intraperitoneal injection of PSG-1 for 4 weeks was shown to relieve oxidative stress, immune dysfunction and age-related injury in the aged mouse brain in a dose dependent manner." (PMID 29344411, 2017).
infection (1 paper, 2023). The state of being infected such as from the introduction of a foreign agent such as serum, vaccine, antigenic substance or organism. "In addition, we observed that the concentration of PSG1, a gal-1 ligand, was increased following infection, providing the first indication of potential regulation of this trophoblast-derived protein in response to insults to maternal health." (PMID 37475853, 2023).
PSG1 also shares sentences with these, for which no sentence is quoted: acute graft versus host disease (1 paper); Arthritis (1); Fetal distress (1); fetal growth restriction (1); gestational diabetes (1); idiopathic pulmonary arterial hypertension (1); ischaemic stroke (1); liver disorder (1); lung adenocarcinoma (1).